DKK1 (dickkopf Wnt signaling pathway inhibitor 1)
Diseases named in the same sentence as DKK1 in open-access papers (continued):
Sharing a sentence is not in itself a finding about the gene and the disease.
cancer (continued). "The activity and expression of DKK1 vary in different cancers, so further exploration of its mechanism is required to verify the prognostic function of DKK1, which can serve as a potential biomarker to accurately predict poor prognosis in patients with these diseases." (PMID 36447119, 2023). "DKK1 inhibits the canonical Wnt signaling pathway that is known to be involved in various cancers." (PMID 35625973, 2022). "The difference in osteocytic DKK1 expression between the different mouse strains may indeed be relevant for preclinical testing of DKK1 inhibitors, which are intensively studied, especially for cancer treatment." (PMID 36552348, 2022). "However, a report recently showed that DKK1 is a Janus-faced cytokine with dichotomous roles in cancer cell metastasis to lung and bone." (PMID 34847079, 2022). "Furthermore, DKK1 acts through the DKK1/CKAP4/PI3K pathway and increases the expression of plasma-membrane-vesicle-associated proteins, which is positively correlated with angiogenesis in cancer cells." (PMID 36012674, 2022). "Although DKK1 is a secreted inhibitor of β-catenin-dependent Wnt signaling, recent studies have shown that its elevated expression correlates with poor prognosis in a range of cancers." (PMID 35712490, 2022). "DKK1 is an antagonist of Wnt signaling, which regulates various cellular and biological processes that play important roles in cell senescence, cell apoptosis, differentiation, and metastasis in various tissues and numerous cancers." (PMID 35619896, 2022). "The role of DKK1 in cancer development remains unelucidated." (PMID 36276289, 2022). "DKK-1 knockdown decreased cancer cell proliferation, migration, and invasion." (PMID 35269944, 2022). "Especially, DKK1 was widely reported to participate cancer development and metastasis." (PMID 35800432, 2022). "Dysregulation of DKK1 has now emerged as an important factor in a variety of human cancers." (PMID 35907982, 2022). "The elevated cAMP further induces the expression of DKK1 in these cancer cells." (PMID 35517499, 2022). "The WNT signaling pathway inhibitor Dickkopf-1 (DKK1) is related to cancer progression." (PMID 36418306, 2022). "The data herein also suggested that metastatic cancer cells in the lung may adapt to high ferroptotic stress and develop resistance to ferroptosis by inducing elevated DKK1 expression." (PMID 35296660, 2022). "The regulation of inflammatory cytokine expression by high DKK1 expression in human cancer raised the question of whether physiological DKK1 activity confers similar functions." (PMID 36539532, 2022). "Both DKK1 and Noggin may be secreted either by cancer cells or by microenvironment cells, such as osteocytes." (PMID 36497192, 2022). "Likewise, the DKK1 protein was readily detectable in the nucleus of cancer cells in our study and DKK1-controlled inflammation was relayed in a cell-autonomous fashion, irrespective of soluble DKK1 abundance." (PMID 36539532, 2022). "Moreover, DKN-01, an IgG4 monoclonal antibody targeting DKK1 has been demonstrated to have therapeutic benefits in gastroesophageal malignancies, indicating the potential of DKK1 in cancer therapy." (PMID 35677557, 2022). "WNT signaling pathway inhibitor Dickkopf-1 (DKK1) is related to cancer progression; however, its diagnostic and prognostic potential have not been investigated in a pan-cancer perspective." (PMID 34899842, 2021). "The function of DKK1 on cancer cells with stem/progenitor cell features suggests that DKK1 may be involved in cancer stem cells-related phenotype development and cancer cell dissemination." (PMID 34093545, 2021). "Taken together, our study annotated DKK1 expression in a pan-cancer manner and identified that DKK1 could be used as an independent prognosis factor." (PMID 34899842, 2021).
cancer (continued). "For example, genes that encode DRs such as DCC, neogenin, UNC5B, UNC5C, or TrkC are repressed in multiple cancer types, while cancer cells can also escape DR‐mediated apoptosis through autocrine overexpression of ligands including DKK1, Netrin‐1, NT‐3, Sema3E, or HGF." (PMID 34542930, 2021). "Consequently, DKK1 has become a promising target for cancer immunotherapy, and the mechanisms of DKK1 affecting cancers and immune cells have received great attention." (PMID 34093545, 2021). "Our findings deepened our understanding of the roles of DKK1 in cancer progression and prognosis." (PMID 34899842, 2021). "Similarly, several studies demonstrated that DKK1 was differentially expressed in a variety of cancers and affected cancer progression by changing cancer proliferation and invasion capabilities." (PMID 34899842, 2021). "We found that the expression level of DKK1 is significantly different in different cancer types." (PMID 34899842, 2021). "In the lungs, DKK1 also reduced the latent transforming growth factor-beta binding protein-1 (LTBP1)-mediated transforming growth factor-beta (TGF-β) secretion of cancer cells by inhibiting Wnt/Ca2+-calmodulin-dependent protein kinase II) (CaMKII)-Nuclear factor-κb (NF-κB) signaling." (PMID 34093545, 2021). "In terms of cancer, the strong duality of the role of DKK-1 is noteworthy." (PMID 34451907, 2021). "Anti-DKK1 antibody suppressed cancer growth and invasive activity." (PMID 34093545, 2021). "Overall, DKK1 is an ideal anti-cancer therapeutic target for immunotherapy." (PMID 34093545, 2021). "DKK1 has not only been evaluated as a prognostic marker in a wide variety of cancers but may also serve as a potential novel treatment target." (PMID 34638464, 2021). "It has been observed that DKK1 shows abnormal expression in various types of human cancers and may promote or inhibit proliferation and invasion in cancer cell lines." (PMID 34697293, 2021). "It has been demonstrated that DKK1 binds to cytoskeleton-associated protein 4 (CKAP4) with high affinity, leading to the activation of Akt by forming a complex between CKAP4 and PI3K, resulting in the proliferation of normal cells and cancer cells." (PMID 33613114, 2021). "Aberrant expression of DKK1 (Dickkopf-1) has been observed in numerous human cancers." (PMID 33613114, 2021). "On the other hand, it has also been shown that DKK1 expression is increased in several cancers." (PMID 34117362, 2021). "Expression level of DKK1 is positively correlated with infiltrating levels of myeloid-derived suppressor cells (MDSCs) in 20 types of cancers, while negatively associated with CD8+ T cells in 4 of these 20 cancer types." (PMID 34093545, 2021). "In addition to mRNA level, DKK1 protein level was found to be increased in both serum and in tissue samples in some specific cancers." (PMID 34093545, 2021). "In addition, the expression of DKK1 was closely related to the clinical stages of several cancer types, including ACC, KIRC, and PAAD." (PMID 34899842, 2021). "Although DKK1 is classified as a Wnt inhibitor, its role in cancer remains controversial." (PMID 33639034, 2021). "The elevated serum level of DKK1 was observed in patients of various cancers with poor prognosis." (PMID 34093545, 2021). "Furthermore, DKK1 showed the ability to modulate immune cell activities as well as the immunosuppressive cancer microenvironment." (PMID 34093545, 2021). "Knockdown of DKK1 in cancer cells inhibited cancer cell proliferation and migration." (PMID 34093545, 2021). "While TET1 was ectopically expressed by ~35-fold in the TET1-CD overexpression T24 cells, several previously identified TET1 target genes, such as TIMP3 and DKK1 in other cancer types, were also induced at 2.1- and 1.8-fold compared to the control cells (EV), respectively." (PMID 32528872, 2020). "Therefore, inhibition of Wnt signaling by secretion of Dickkopf WNT signaling pathway inhibitor 1 (DKK1) is one mechanism by which cancer cells enter quiescence." (PMID 32300189, 2020).
cancer (continued). "It proposed concept that the microenvironment in the secondary organs might restrict the role of Dkk-1 in cancer metastasis." (PMID 33384994, 2020). "Overexpression of DKK1, an identified proinflammatory cytokine in quite a number of cancers, could boost malignant cell proliferation, migration, and invasiveness and give rise to unfavorable clinical outcomes in HNSCC." (PMID 33193693, 2020). "Accumulated clinical evidence had demonstrated that high levels of Dkk-1 were correlated with poor overall survival in various cancers, which suggested that Dkk-1 might be as a prognostic marker." (PMID 33384994, 2020). "Dickkopf-1 (DKK1), a secreted protein, plays different roles in different types of cancers." (PMID 31285694, 2019). "DKK1 expression appeared quite variable between and within cancer types." (PMID 31069116, 2019). "Based on the ability of DKK-1 to inhibit β-catenin-dependent Wnt signaling, a pathway that is frequently dysregulated in cancer cells, DKK-1 has been widely investigated in oncology and is now considered an attractive therapeutic target for anti-cancer therapy." (PMID 30420710, 2018). "DKK1 has been proposed as a potential biomarker for cancer progression and prognosis." (PMID 30028084, 2018). "Notably, we observed that methylation of DKK1 is high in BRAF mutant and CIMP (CpG island methylator phenotype)-positive cancers, whereas AXIN2 methylation appears to be associated with CMS4." (PMID 28368388, 2017). "Mechanisms leading to upregulation of DKK1 in many cancers are beginning to emerge." (PMID 27367730, 2016). "Reducing the amount of circulating DKK1 may reveal a simple and efficient strategy to limit or reverse cancer growth." (PMID 27367730, 2016). "However, there are conflicting studies showing down regulation or silenced expression of DKK1 in cancers." (PMID 27367730, 2016). "Together, these studies suggest that levels of DKK1 might serve as a prognostic tool of cancer initiation and progression." (PMID 27367730, 2016). "This study suggested that DKK1 could serve as a marker for MM progression and that cancer mediated modulations of DKK1 influences bone metabolism." (PMID 27367730, 2016). "Moreover, there are numerous cancers with downregulation of extracellular Wnt inhibitors such as DKK1, sFRP and Wif1 that make the development of therapies targeting the Wnt ligand-receptor complex low hanging fruit." (PMID 27598201, 2016). "Consequently, dysregulation in any steps of the Wnt/β-catenin signal including DKK1-mediated repression leads to numerous developmental abnormalities and diseases, with the most widely studied being cancer." (PMID 27367730, 2016). "So, DKK1 levels increased in serum from cancer patients whether resulted from treatment interferences remain unclear." (PMID 26799283, 2016). "Their report was the first to show that DKK‐1 as a highly immunogenic antigen could induce an autoantibody response in cancer." (PMID 26988995, 2016). "Since SOST’s role in cancer has been minimally explored, it also remains to be elucidated whether this molecule, similar to DKK1 has context-dependent effects on cancer." (PMID 26545120, 2015). "In the last decade, DKK1’s role in cancer has been controversial." (PMID 26545120, 2015). "Paradoxically, however, DKK-1 modulates proliferation and survival of cancer cells in which the Wnt/β-catenin pathway is constitutively activated by mutations in genes encoding intracellular pathway components, or independently of β-catenin transcriptional activity." (PMID 25788273, 2015). "Future studies that would potentially elucidate the context-dependent role of DKK1 in cancer progression and metastasis would be: dissecting out the cell- and non-cell autonomous effects of DKK1, and using genetics to characterize the correlative vs. the causative effects of DKK1." (PMID 26545120, 2015). "The inhibition of Wnt signaling by DKK1 is a frequent event in diverse human cancer." (PMID 26101916, 2015).
cancer (continued). "Interestingly, miR-203 inhibits cancer stem cell maintenance by self-renewal inhibition through indirect induction of DKK1, a secreted antagonist of the canonical Wnt pathway." (PMID 26132195, 2015). "Therefore, the different function of DKK-1 in different cancer types depends on the histological type of the cancer cells and the tissue microenvironment." (PMID 25116444, 2014). "Another possibility was that the cancer cells may be responsive to Dkk1 differently in 2-D versus 3-D cultures, which more closely mimic the in vivo environment." (PMID 25499541, 2014). "DKK1 expression was highly transactivated in the great majority of these cancer lines." (PMID 24391982, 2013). "DKK-1 has multiple biological roles in a variety of cancers." (PMID 21029453, 2010). "It has been advocated that ASCL1 expression may favour cancer cell growth through repression of DKK1 with the consequential aberrant activation of the Wnt/β-catenin signalling pathway." (PMID 19744316, 2009). "Nonetheless, we found a large amount of DKK-1 in serologic samples from cancer patients and an enhanced DKK-1 gene expression in CaP tissues, suggesting that the increased serum DKK-1 levels in CaP patients might depend on the CaP cell secretion." (PMID 18978943, 2008). "We thus propose that down-regulation of MYCN in Daoy cancer cells after Msi1 depletion might induce expression of the Wnt repressor DKK1, therefore interconnecting Msi1, Wnt and Hedgehog signaling pathways." (PMID 18826648, 2008). "Interestingly, DKK1 expression in cancer has been described previously, mainly in multiple myeloma, hepatoblastomas and Wilms' tumours." (PMID 17245340, 2007). "In this study, we report the expression of Dickkopf-1 (DKK1) in multiple common cancers." (PMID 17245340, 2007). "Altogether, these data suggest that DKK1 is a shared antigen expressed in multiple cancer types." (PMID 17245340, 2007). "Expression of DKK1 in some cancer cell lines was also confirmed by real time RT–PCR." (PMID 17245340, 2007). "Consequently, the combination of anti-DKK1 and anti-PD/PDL-1 therapy could be a possible hallmark in cancer treatment." (PMID 39795613, 2025). "Therefore, targeting DKK1 may be pivotal in boosting the efficacy of cancer immunotherapy and enhancing CRC patient prognosis." (PMID 39788945, 2025). "Notably, DKK1 has been shown to sensitize cancer cells to alkylating agents, which induce apoptosis, highlighting the potential therapeutic implications of targeting Wnt pathway regulation in chemotherapy-resistant cancers." (PMID 40430852, 2025). "Therefore, further studies on the role of DKK1 in cancer are warranted." (PMID 38376441, 2024). "Furthermore, DKK1 and LRP6 can form a ternary complex with cytoskeleton-associated protein 4 (CKAP4), a cell surface receptor that activates PI3K/AKT signaling, to enhance DKK1-dependent cancer cell proliferation." (PMID 37759431, 2023). "Interestingly, latent competent cancer cells expressing SOX2/SOX9 increase dormant CSCs (or latency-competent cancer cells) that downregulate NKG2DL through a unique mechanism that produces the WNT inhibitor DKK1, thus evading NK cell-mediated immunity." (PMID 37394580, 2023). "However, more evidence had shown that DKK1 may play a role in cancer progression as it inhibits the activation of β-catenin to allow cancer cells to have stem cell-like properties to avoid natural killer cells." (PMID 37086261, 2023). "Therefore, DKK1 is emerging as an important target for cancer therapy." (PMID 37190019, 2023). "Thus, DKK-1 may be an important marker for predicting cancer progression in patients with early malignancies." (PMID 38067123, 2023). "Moreover, DKK1 is associated with the so-called immune-desert microenvironment that results from the activation of MDSC and downregulation of natural killer cells in the cancer milieu." (PMID 35121803, 2022).
cancer (continued). "Furthermore, prognostic analysis of DKK1 expression in clinical samples from multiple cancers including gastric, lung, pancreatic, and head-neck squamous cell cancer (head-neck SCC) consistently revealed that patients with higher DKK1 expression exhibited worse overall survival outcomes." (PMID 35296660, 2022). "Thus, DKK-1 may be a novel therapeutic target to inhibit cancer cell proliferation, migration, invasion, and angiogenesis." (PMID 35269944, 2022). "Interestingly, DKK-1 expression would play a dual role in childhood cancers." (PMID 34451907, 2021). "Therefore, FOXM1 may be a molecular target which present a synergistic clinical effect for cancers which express it as well as DKK1 and CKAP4." (PMID 34117362, 2021). "The increase in DKK1 expression in cancer may be a result of aberrant activation of Wnt signaling." (PMID 34117362, 2021). "The effect of DKK1 on various cancers may be the result of abnormal activation of WNT signaling." (PMID 34899842, 2021). "Furthermore, functionally, ectopic expression of TET1 catalytic domain in cancer cell lines reactivated silenced tumor-suppressor genes (DLit2, ZNF382, HOXA9, and DKK1) and significantly suppressed clonogenicity of cancer cells compared to the catalytically dead mutant." (PMID 34209564, 2021). "There was a positive correlation between the mRNA level of CTNNB1 and DKK1 according to our calculation, supported by the similar evidence from protein expressions in several types of cancers, suggesting that the elevation of DKK1 may be attributed to overactivation of Wnt signaling." (PMID 34093545, 2021). "Thus, DKK-1 is not only a target of statin but it directly regulates the expression of molecules involved in a plethora of biological functions, thus expanding its role, which has been so far restricted mainly to cancer." (PMID 30420710, 2018). "Therefore, the regulation of DKK1 may be a therapeutic target in the development of anti-cancer therapy." (PMID 28178355, 2017). "Furthermore, high circulating DKK1 levels correlate with poor prognosis in various cancers." (PMID 28178355, 2017). "Thus, another explanation for the positive relationship between serum DKK1 levels and poor PC prognosis is that elevated DKK1 could enhance the metastatic potential of cancer cells." (PMID 26101916, 2015). "These cancers, through their heavily methylated phenotype have been found to methylate other inhibitors of the Wnt pathway such as DKK1 and AXIN2, which indicates epigenetic regulation of the Wnt pathway may be more prevalent in the BRAF mutant/MSI compared to other CRC subtypes." (PMID 25613750, 2015). "Moreover, we show that DKK-1 regulates several cancer-related genes including the cancer stem cell marker aldehyde dehydrogenase 1A1 (ALDH1A1) and Ral-binding protein 1-associated Eps domain-containing 2 (REPS2), which are involved in detoxification of chemotherapeutic agents." (PMID 25788273, 2015). "Moreover, several studies indicate that DKK-1 expression is downregulated along colorectal adenoma-carcinoma transition and at late CRC stages but the clinical consequences are unknown." (PMID 25788273, 2015). "DKK1 might play diverse biological roles in different type of cancer cells." (PMID 24391982, 2013). "Third, although there is no report so far for an impact of DKK1 mutations on bone mass in humans, there is hallmark evidence for an over-production of DKK1 in human cancer cells being responsible for the development of osteolytic lesions associated with metastatic bone disease." (PMID 20436912, 2010). "Elevated expression of transcriptional regulator inhibitor of DNA binding 1 (ID1) promoted cancer cell‐mediated vasculogenic mimicry (VM) through regulation of pro‐angiogenic and pro‐cancerous genes (e.g. VE‐cadherin (CDH5), TIE2, MMP9, DKK1)." (PMID 40116596, 2025). "The interaction between DKK1 and CKAP4 activates the PI3K/AKT signaling pathway, promoting cancer cell proliferation." (PMID 41149482, 2025).